PLAU (plasminogen activator, urokinase)
Diseases named in the same sentence as PLAU in open-access papers (continued):
Sharing a sentence is not in itself a finding about the gene and the disease.
mesenchymal tumors (1 paper, 2023). "The combination of the expression of the genes PLAU, LAMB1, COL6A1, and TGFBI classified correctly the majority of mesenchymal tumors." (PMID 38031074, 2023).
metastatic cancers (1 paper, 2023). A carcinoma which has spread from the original site of growth to another anatomic site. "Lastly, plasminogen activator (PLAU) is also associated with the complex phenotype of human cancer, and its upregulation promotes metastatic cancers." (PMID 37122535, 2023).
oral cavity cancer (1 paper, 2021). A primary or metastatic malignant neoplasm involving the oral cavity. "Specifically, an independent sample t test was performed on mRNA expression data of the CDKN2A and PLAU genes between OSCC (only oral cavity cancer was selected from HNSCC) and normal tissues." (PMID 33968767, 2021).
parasite infection (1 paper, 2022). "Genes encoding CLU, SPARC and PLAU, were also higher more than 1fold, log2 in Holstein cells and modulated by parasite infection." (PMID 35061738, 2022).
Peritoneal Fibrosis (1 paper, 2025). Disorder characterized by a wide range of structural changes in PERITONEUM, resulting from fibrogenic or inflammatory processes. "Studies have shown that PLAU and CTSS are involved in signaling pathways related to apoptosis and cell migration, which are also implicated in peritoneal fibrosis." (PMID 40620673, 2025). "However, our findings showed that SAL does not have a significant impact on the expression of PLAU or CTSS, indicating that they are not the focus of SAL in reducing peritoneal fibrosis." (PMID 40620673, 2025).
renal tumors (1 paper, 2017). "Specifically, the transcript expressions of AKR1C1, S100A2, PLAU, SLC3A2, TBC1D2, and WIZ were decreased, while expressions of TGM2, SLC7A5, and NMI were increased in renal tumors when compared with non-tumorous control samples." (PMID 29272308, 2017).
skin aging (1 paper, 2023). The gradual irreversible changes in structure of skin that occur as a result of the passage of time.. "Then, we confirmed the down-regulated expressions of ABCC4, PTGER3, BCEH, HPGD, and MOXD1 in normal group, while AR, CXCR2, HSD17B2, ODC1, PI3, PLAU and THBS2 were up-regulated in skin aging group." (PMID 37310405, 2023).
thyroid tumor (1 paper, 2010). A benign or malignant neoplasm affecting the thyroid gland. "Interestingly, the ligands PLAU and SPP1 have previously been associated with invasion and progression in several types of solid tumors, and both in vivo and in vitro models have demonstrated overexpression of these ligands in thyroid tumors." (PMID 20877637, 2010). "Some internal validations emerged, such as the pairs PLAU/PLAUR, SPP1/CD44, and SPP1/ITGA9, whose ligands have been demonstrated overexpressed in thyroid tumors as well as in our in vitro model." (PMID 20877637, 2010).
triple-negative breast carcinoma (1 paper, 2022). An invasive breast carcinoma which is negative for expression of estrogen receptor (ER), progesterone receptor (PR), and human epidermal growth factor receptor 2 (HER2). "Overexpression of PLAU has been identified as a promising therapeutic target for inhibition in (co)treatment of triple negative breast cancer in multiple studies, including ours." (PMID 36672610, 2022). "Treatment of the hormone-insensitive, aggressive MDA-MB-231 triple negative breast cancer cell line with WA led to a decreased PLAU expression and reversed its highly invasive metastatic phenotype." (PMID 36672610, 2022).
tumor (302 papers, 1993 to 2026). "For instance, COL3A1 plays a role in ECM stiffness and tumor invasion in both squamous and adenocarcinoma types, and PLAU and SPP1 have been implicated in promoting tumor cell migration and metastasis via interactions with integrins and the PI3K/AKT pathway." (PMID 41465316, 2025). "In CC, PLAU is often overexpressed, and this upregulation has been linked to poor prognosis, enhanced metastatic potential, and tumor progression, primarily through its role in promoting epithelial-mesenchymal transition." (PMID 40599331, 2025). "The interaction analysis with tumour size also showed that PLAU expression was a significant factor affecting all‐cause mortality only in the population with a large tumour size (≥T3), and the interaction term was also significant." (PMID 38363001, 2024). "GO enrichment analysis, KEGG pathway analysis, and GSEA analysis results indicated that PLAU was associated with aggressive tumor behavior and tumor immune microenvironment." (PMID 39511134, 2024). "PLAU (p < 0.01) was expressed higher both in normal and tumor tissues, but its association with worse OS was consistent with what we found before." (PMID 36003146, 2022). "Collectively, PLAU is necessary for tumor progression and can be a diagnostic and prognostic biomarker in HNSCC." (PMID 34093649, 2021). "PLAU encodes a serine protease involved in degradation of the extracellular matrix and possibly in tumour cell migration and proliferation." (PMID 34358255, 2021). "PLAU and its receptor were upregulated in tumor cells and were associated with tumor proliferation, migration and metastasis." (PMID 33968767, 2021). "The Cancer Genome Atlas (TCGA) was used for analyzing the association between FOXM1/PLAU and tumor immune infiltration." (PMID 31949481, 2020). "We observed that IDO1, IL20RB, PPP3CA, and PLAU were negatively associated with favorable outcomes and were found to participate in tumor progression, whereas ESR2 showed the opposite effect." (PMID 33718118, 2020). "PLAU has been shown to be a novel biomarker with high tumour expression levels in HNSCC and is linked to decreased survival rate, increased disease progression and relapse." (PMID 31443700, 2019). "PLAU (plasminogen activator, urokinase) encodes a serine protease involved in degradation of the extracellular matrix facilitating tumour cell migration and proliferation." (PMID 31443700, 2019). "PLAU, which encodes plasminogen activator urokinase and serves as a biomarker for tumor invasion, was found to be consistently activated in the samples with the highest MAII scores." (PMID 29299133, 2017). "The PLAU gene encodes plasminogen activator, a serine protease involved in degradation of the extracellular matrix and possibly tumor cell migration and proliferation." (PMID 23799036, 2013). "The PLAU gene encodes urokinase plasminogen activator, a multifunctional protein that can promote tumor invasion and metastasis in several malignancies, including PCa." (PMID 22547956, 2011). "The PLAU gene encodes urokinase plasminogen activator, a multifunctional protein that can promote tumor invasion and metastasis in several malignancies including prostate cancer." (PMID 22191037, 2011). "Methylation and Tumor Immune Dysfunction and Exclusion (TIDE) analyses revealed that PLAU upregulation was most likely caused by hypomethylation and that high PLAU expression may be associated with tumor immune evasion in HNSCC, respectively." (PMID 36266384, 2022). "The protein encoded by the PLAUR gene is the receptor of PLAU (plasminogen activator, urokinase), which plays a momentous role in the migration and proliferation of tumor cells through remodeling of the extracellular matrix and the tumor microenvironment." (PMID 35222525, 2022). "In addition, as the up-regulated differential RNA exhibiting the most TF activity, PLAU encodes a serine protease that acts as an activator in the ECM degradation in tumor development." (PMID 29351231, 2018).
tumor (continued). "Interestingly, a DETG that encodes the plasminogen activator, urokinase (PLAU), a known biomarker for tumor invasion, was consistently upregulated in samples positive for the four TFFGs (PML-RARA, RUNX1-RUNX1T1, TMPRSS2-ERG, and SFPQ-TFE3)." (PMID 29299133, 2017). "For example, the gene encoding protease urokinase-type plasminogen activator (PLAU/uPA) is hypomethylated and over expressed in conjugation with tumour progression in breast cancers, with increased uPA expression resulting in increased tumour aggression and poor clinical outcome." (PMID 26220712, 2015). "Importantly, the PLAU expression level was significantly associated with tumor grades." (PMID 34093649, 2021). "Zhao’s research have suggested that PLAU is involved in extracellular matrix remodeling and cell migration, which are essential for tissue repair and tumor progression." (PMID 41582652, 2026). "TGFB1 is essential for invasive growth and proliferation in GC tumor cells, such as GCTM-1 GC cell line, in which TGFB1 induces enhanced expression of matrix metalloproteinase 9 (MMP9) and PLAU in tumor cells." (PMID 40075643, 2025). "PLAU is a serine protease that promotes tumor cell migration and invasion by converting plasminogen to plasmin, which facilitates extracellular matrix degradation." (PMID 41048340, 2025). "We found that macrophages, which served as the source cells of tumor, showing stronger interaction strength with other cell types, especially fibroblasts and hepatocytes, and the SPP1, PTN, CCL, TGFB1 and PLAU pathways were more enriched in tumor regions." (PMID 40230843, 2025). "PLAU plays a role in tumor progression by promoting tumor cell proliferation and also promoting cell migration, invasion, and EMT." (PMID 40143204, 2025). "MiR-193b was demonstrated to negatively regulate tumor migration, invasion and metastasis through targeting urokinase type plasminogen activator (PLAU), dimethylaminohydrolase 1 (DDAH1), cyclin D1 (CCND1) and ETS1 in several cancer cell lines." (PMID 39972491, 2025). "PLAU is involved in tumor cell migration and invasion, and previous study had confirmed the relationship between PLAU and OS in TCGA cohort." (PMID 38336764, 2024). "In conclusion, Kaplan–Meier and Cox analyses of PLAU expression with P. gingivalis infection showed the potential of PLAU as a molecular prognostic marker in advanced HNSCC patients with tumour sizes ≥T3 or advanced HNSCC patients with lymph node metastases." (PMID 38363001, 2024). "Hallmark analysis revealed lower apoptosis levels in tumor cells, marked by BAX and PLAU, indicating their unique roles." (PMID 38988712, 2024). "In the single-cell map of our study, the overexpressed PLAU was mainly distributed in malignant epithelial cells of tumor tissue." (PMID 39511134, 2024). "Conversely, STING activation supresses migration of cancer cells and tumour-infiltrating neutrophils by reducing translation of the matrix-remodelling serine peptidase PLAU." (PMID 38084916, 2024). "Promoter methylation analysis demonstrated that MRC2, OLFML2B, and PLAU were differentially and highly methylated in primary tumor cells compared with normal cells." (PMID 37340445, 2023). "PLAU which is overexpressed in numerous tumours serves as essential for the growth and spread of tumours." (PMID 37927475, 2023). "PLAU (plasminogen activator urokinase) mRNA has also been shown to be significantly elevated in HNSCC tumour samples over normal specimens, with evidence for PLAU as an independent indicator for HNSCC prognosis associated with poorer clinical outcomes." (PMID 35327656, 2022). "We examined the extent to which F3 and PLAU expression overlapped in the cancer cells of each tumor." (PMID 35053621, 2022). "In the present study, PLAU was upregulated in tumor tissues and was related to OS in the cohort of TCGA and GEO datasets." (PMID 35912229, 2022).
tumor (continued). "As previously reported, PLAU and its receptor PLAUR were involved in regulating cell adhesion and promoting tumor cell migration, while c-Myc and AXL were associated with EMT, invasiveness, and migration." (PMID 35680853, 2022). "As the soluble form of membrane-bound urokinase plasminogen activator receptor, PLAU is expressed in various cell types, such as neutrophils, monocytes, lymphocytes, endothelial cells and tumour cells." (PMID 36177176, 2022). "Most of these genes were tumor cell metastasis-associated genes such as TNC, PLAU, PDPN, SPARC, LUM, and especially SNAI2 (Zinc finger protein SLUG transcription factor)." (PMID 35742914, 2022). "Genes overexpressed in tumor-associated macrophages compared to normal adrenal macrophages included PLXDC1 and PLAU (log2FC > 0.5, BH adj." (PMID 36271074, 2022). "The results showed that the ITGA5 and SERPINE1 proteins were mainly expressed in HNSCC tumor cells (with medium staining), while the PLAU protein was enriched in the extracellular matrix of HNSCC (with strong positive reaction)." (PMID 36425786, 2022). "Even when included in the expanded analysis of 337 normal samples from the GTEx database, our results suggested that PLAU still significantly overexpressed in tumor tissue." (PMID 35141223, 2022). "Conversely, tumor-associated macrophages (TAM) expressed high levels of PLAU and PLAUR, and tumor-associated endothelial cells expressed high levels of PLAT, F2R and SERPINE1." (PMID 35053621, 2022). "IL8 also upregulated PLAU secretion of tumor cells, which is also reversed by SB225005, a CXCR2 inhibitor." (PMID 33574243, 2021). "PLAU in tumor cells further promotes ESCC cell proliferation and invasion by activating the classic MAPK pathway." (PMID 33574243, 2021). "PLAU upregulation in primary tumor tissues is positively correlated with distant metastasis and indicates poor patient prognosis in CRC." (PMID 33750326, 2021). "Here, we applied multiple datasets to evaluate the increased expression of PLAU in HNSCC tumor samples as compared to adjacent tissues and confirm it as an independent prognosis predictor of HNSCC patients in different angles and levels." (PMID 33520474, 2021). "In the perspective of PLAU as well as its most correlated genes, the EMT process was the most enriched pathway, further identifying the role of PLAU in tumor invasion and metastasis." (PMID 34093649, 2021). "Age, clinical stage, tumor size, neck lymph node status, HPV positivity and PLAU expression was considered to be significantly associated with overall survival time in univariate cox analysis of 496 HNSCC patients." (PMID 33520474, 2021). "The mRNA expression of the CDKN2A and PLAU genes in OSCC tumor tissues was higher than that in normal tissues." (PMID 33968767, 2021). "PLAU is overexpressed in many tumors and plays an important role in tumor development and metastasis." (PMID 33574243, 2021). "Overexpression of PLAU/PLAUR was found to be significantly associated with clinical variables including age, tumor type, WHO grade, histology, IDH-1 mutation, and 1p19q status." (PMID 35087738, 2021). "For instance, the plasminogen activator (PLAU) can degrade the matrix surrounding a tumor and promote the migration of cells to distant organs, thereby inducing tumor cell invasion, migration, and homing to distant organs." (PMID 34149807, 2021). "The mRNA expressions of PLAU and PLAUR varied remarkably among different ages, tumor histology, WHO grades and tumor types, IDH-1 mutation, and 1p19q status and other clinical characteristics." (PMID 35087738, 2021). "There was no significantly different expression of PLAU mRNA in different age, gender, clinical stage, and tumor stage, but the difference of PLAU in HPV positivity and neck node status was considered as significant (p = 0.001, p = 0.033, respectively)." (PMID 33520474, 2021).
tumor (continued). "Some studies report that the expression level of PLAU is significantly correlated to tumor cell lymph node and distant organ metastasis." (PMID 33520474, 2021). "In vivo, the knockdown PLAU group exhibited reduced tumor growth and weight than the control group, while the PLAU overexpression group exhibited increased tumor growth and weight compared with the control group." (PMID 33574243, 2021). "Except for some inflammation-related signaling pathways, several tumor-related signaling pathways have a relationship with PLAU and PLAUR co-expression networks." (PMID 35087738, 2021). "As expected, the expression of IL20RB, MET, OASL, and PLAU in tumor tissues was significantly higher than that in normal tissues." (PMID 34335699, 2021). "The difference in expression comparing tumor and normal tissues were found to be significant in eight genes (PLAU, EGR1, IL6, EGFR, EZH2, BMP4, CCNB1, NMI)." (PMID 34077304, 2021). "Further, this work provided a four molecular pathway foundation (ANXA2/HMGA1/POU3F1; NFRSF13/GSN; TMOD3/RAI14/VWF; PLAT/PLAU) behind HO-1 regulation of tumor cytoskeletal cell compartments." (PMID 32197509, 2020). "Bioinformatics analysis indicated that FOXM1+PLAU+ associated genes are enriched in TGF-beta, DNA repair and drug resistance signaling pathways; FOXM1 and PLAU expression are negatively correlated with tumor immune infiltration." (PMID 31949481, 2020). "Tumor cells modulate their local environment to gain invasive properties by releasing ECM degrading proteases such as PLAU." (PMID 31454892, 2019). "In cancer, aberrant expression of PLAU and PLAUR has been linked to tumor progression, metastasis, and shortened survival in cancer." (PMID 28881803, 2017). "Histological and immunofluorescent analyses showed restored cellularity and tumor neo-angiogenesis in FOXM1b- or PLAU-expressing GICs that were devoid of HMGA2." (PMID 27259253, 2016). "The integration from our omics-based research provides a four molecular pathway foundation (ANXA2/HMGA1/POU3F1; NFRSF13/GSN; TMOD3/RAI14/VWF; and PLAT/PLAU) behind HO-1 regulation of tumor cytoskeletal cell compartments." (PMID 28032857, 2016). "PLAU, a serine protease involved in degradation of the extracellular matrix and possibly tumor cell migration and proliferation was also overexpressed in our ATC data." (PMID 25887408, 2015). "Urokinase-plasminogen activator or PLAU gene is known to encode uPA, the protease which degrades ECM and plays critical roles in cell migration, tissue remodeling, angiogenesis, tumor invasion, and metastasis." (PMID 24971065, 2014). "The uPA (urokinase-type plasminogen activator/PLAU) and its main inhibitor PAI1 play key roles in tumour-associated processes and their elevated expression is correlated with negative outcomes in node negative breast cancer." (PMID 24229053, 2013). "MMP-9 and PLAU were the most important degradation enzymes of extracellular matrix, while degradation of extracellular matrix was a necessary process during tumor invasion, and metastasis." (PMID 24379889, 2013). "In CRC, however, SLC46A1 downregulation induces intracellular folate deficiency, triggering locus-specific DNA hypomethylation at the FOS promoter, which activates oncogenic transcription of key downstream effectors (CCND1, BCL2, PLAU), driving tumor progression." (PMID 41620398, 2026). "Our study revealed PLAU’s role in tumor progression specifically in the context of SCAFs." (PMID 39834857, 2025). "Furthermore, we validated the role of SCAF-secreted plasminogen activator urokinase (PLAU) in tumor progression and the cultivation of immunosuppressive TME of PDAC through in vitro and in vivo experiments." (PMID 39834857, 2025). "PLAU was involved in angiogenesis, cell migration and invasion, and GREM1 was associated with the transforming growth factor (TGF)-beta signaling pathway, which was important for tumor progression and immune evasion." (PMID 41048340, 2025).